TNF (tumor necrosis factor)
Diseases named in the same sentence as TNF in open-access papers (continued):
Sharing a sentence is not in itself a finding about the gene and the disease.
glioma (continued). "The essential pathways of luteolin against glioma involve pathways in cancer, the PI3K-Akt signaling pathway, the TNF signaling pathway, and more." (PMID 34873410, 2021). "We demonstrate that glioma cell-derived IL8 and CCL2 stimulate GAMs to secrete TNFα and promote EC activation." (PMID 33853689, 2021). "TIME cluster A exhibited the high expression profiles of ZEB1, TNF, and LAG3; while GZMA, CXCL9, CXCL10, and CD8A were relatively overexpressed in TIME cluster C. EMT is a common process of paramount importance in glioma occurrence and invasion." (PMID 34650972, 2021). "Bioactive triterpenoid ursolic acid (UA) isolated from Rosmarinus officinalis was found to suppress IL-1β/ TNF-α and downregulate MMP-9 protein in rat glioma cells, thereby preventing cancer cell proliferation." (PMID 34439380, 2021). "Interestingly, TNF, which could induce the apoptosis of ECs, was detected in glioma but did not inhibit the associated angiogenesis." (PMID 33300633, 2021). "Here, we performed bioinformatic analyses for TNFSF13 (also known as APRIL), a proliferation-inducing ligand of the tumor necrosis factor (TNF) superfamily, aiming to assess its potential for predicting glioma patient’s prognosis and targeted therapy." (PMID 34712225, 2021). "Ganoderma lucidum polysaccharides (GL‐PS) increased the concentration of serum IL‐2, TNF‐α and IFN‐γ and enhanced the cytotoxic activity of natural killer cells and T cells, inhibited glioma growth and prolonged the survival of rats." (PMID 34302428, 2021). "The data shown in our study indicate that overexpressed JMJD1C increases the expression of M1 markers (IL‐1β, TNF, CXCL9, IL‐23, ROS1, IL‐12a, and IL‐12b) both in the glioma mouse models and in the CD14+ monocytes co‐cultured with glioma cells." (PMID 34586733, 2021). "In our studies, we found that the both the mRNA and protein levels of TNF-α, RIP1, RIP3 and MLKL were increased in glioma cells treated with emodin in vivo and in vitro for the first time." (PMID 30924024, 2020). "The brown module was found to be strongly related to WHO grade of gliomas, and KEGG pathway analysis demonstrated that TNFRSF1A was enriched in MAPK signaling pathway and TNF signaling pathway." (PMID 32257943, 2020). "TNF-α activated the NF-kappa B pathway and significantly upregulated the expression of PKM2 in glioma cells." (PMID 32382013, 2020). "CPMV has been shown to stimulate IFN-γ and TNF-α in the TME in our previous studies, and therefore is likely to influence the glioma TME similarly." (PMID 30974896, 2019). "Combining the results obtained by silencing or over-expressing NFATc3, this study indicates that this member is involved in RCAN1-4, COX-2, TNF-α, IL-2, GM-CSF and CXCR-3 gene regulation in U251 glioma cells." (PMID 31249342, 2019). "In glioma cell lines with inhibited NF-κB expression, BIRC3 expression is also inhibited and these cells are sensitive to TNF-α induced cell death." (PMID 27074575, 2017). "Expression analysis of cytokines secreted by glioma cells co-cultured with MCs, revealed a significant increase in expression of CXCL10, CXCL12 and TNF-α." (PMID 28445977, 2017). "In this study, we demonstrated that Bcl-2 was downregulated while the level of Bax, cleaved caspase-3, and TNF-α was increased significantly by RBM5 in gliomas cells, which suggest that RBM5, at least partly, promoted cell apoptosis in gliomas cells." (PMID 28061901, 2017). "Experimental evidence indicates that NF-kappaB signaling pathway is the link between TNF-α and PTEN in leukemic, glioma and intestinal cells." (PMID 27562094, 2016). "The inhibition of p38 triggers the TNF-mediated and caspase-dependent apoptotic pathway in human lymphoma U937 cells and increases sensitivity to the cytotoxic effect of TMZ in human glioma U87MG cells." (PMID 27074557, 2016). "TNF-α recruits p65 and p50 subunits of NF-κB to the CHI3L1/YKL-40 promoter, suppressing the expression of YKL-40 in glioma cell lines." (PMID 24809021, 2014).
glioma (continued). "The resistance of gliomas to apoptosis, induced in one scenario by TNF-α, is possibly due to the release of cytokines IL-6, IL-8, and MCP-1, in fact, in response to TNF-α treatment." (PMID 25411122, 2014). "Furthermoe, the levels of several NF-κB target genes, TNF-α, IL-6, CCND1, MYC, BcL-XL and MMP-9, were upregulated in Bmi-1-overexpressing, but downregulated in Bmi-1-silenced glioma cells." (PMID 23383216, 2013). "In cultured glioma cell lines as well as human GBM xenografts, we found that TNF-α treatment activated both the NF-κB and STAT3 pathways, in a temporal manner." (PMID 24244348, 2013). "In conclusion, the present data indicated prognostic significance of Cygb in gliomas: correlation with PI3K, Akt, IL-6, TNFα, VEGF, microvessel morphometry and survival of patients with gliomas." (PMID 23688241, 2013). "Tumor necrosis factor (TNF)-related apoptosis-inducing ligand (TRAIL) and paclitaxel (PX), in combination or alone, was used to treat U87-MG human glioma cells (U87 cells) or U87-SLCs." (PMID 22942757, 2012). "Significant differences in the concentrations of IFN-γ, TNF-α, and IL-5 were observed only when NY-ESO-1 specific T cells were co-cultured with decitabine-treated T98 glioma cells (p < 0.0001)." (PMID 22060015, 2011). "Do presented a study on tumor necrosis factor alpha (TNF-alpha) and interferon gamma (IFN-gamma) induced NO production in glioma cells." (PMID 22072995, 2011). "This study aimed to investigate the relationship between serum inflammatory markers (TNF-α, IL-6, CRP) and cerebrospinal fluid (CSF) cytokine levels (AVP, OT, β-EP) with the severity of postoperative neurological injury and prognosis in patients with glioma." (PMID 41394380, 2025). "In glioma and sarcoma models, CAR T cells engineered with Zip18R displayed significantly greater antitumor efficacy than unmodified CAR T cells, with enhanced persistence and elevated secretion of effector cytokines such as IFN-γ, IL-2, and TNF-α." (PMID 40895575, 2025). "TNF‐α/NF‐κB signaling is another key inflammatory axis: TNF‐α can stimulate glial and immune cells to produce IL‐6 and activate NF‐κB, which in turn sustains STAT3 signaling, thereby enhancing glioma cell proliferation and aggressiveness." (PMID 41354084, 2025). "Similarly, the mRNA expression levels of STAT3, IL-6, and TNF-α, which are crucial factors in the STAT3 pathway, were elevated in glioma tissues compared to paracancerous tissues." (PMID 38495483, 2024). "In this context, pro-immunogenic mediators interferon-gamma (IFN-γ), tumor necrosis factor-alpha (TNF-α), and interleukin-2 (IL-2) have been shown to be upregulated in glioma surroundings after injection of miR-124 mimics, leading to a significant anti-glioma therapeutic impact." (PMID 39007129, 2024). "Similarly, ATOR increased the production of TNF-α and IFN-γ, inhibited PD-L1, and suppressed immune escape from gliomas." (PMID 39726023, 2024). "In vitro, when bone-marrow derived macrophages from Bai1−/− mice were in co-culture with human glioma cells infected with HSV, the expression of TNFα by Bai1−/− macrophages was decreased compared to wild-type macrophages, suggesting that BAI1 downstream activation leads to TNFα expression increase." (PMID 39196415, 2024). "A study showed that intra tumoral (IT) injection of antigen‐pulse DC cells improves the TME by reducing TGF‐β,87 increasing TNF‐α and IFN‐γ, promoting proliferations of CD8+ T cells, reducing Tregs activation, and increasing the survival rate of mice with glioma." (PMID 36464889, 2023). "Overall, non-classical monocytes had the highest levels of both TNF and IL-12; moreover, this was further up-regulated in glioma patients." (PMID 36768201, 2023). "The antitumor cytotoxic T cell activity of T-αFGL2 cells against the FGL2-expressing murine glioma cell line, DBT, was evaluated by measuring the proportion of live glioma cells and granzyme B+, interferon γ (IFNγ)+, and tumor necrosis factor α (TNFα)+ T cells." (PMID 36759517, 2023).
glioma (continued). "The proinflammatory cytokines (TNF, IL-12) were dominantly expressed by non-classical monocytes in glioma patients." (PMID 36768201, 2023). "In addition, ELISA results showed that CD8+ T‐cell supernatants cocultured with M2‐Exos‐cultured glioma cells showed lower levels of IFN‐γ, TNF‐α, and Gzmb secretion." (PMID 37097629, 2023). "Non-classical monocytes from the glioma patients exhibited a proinflammatory cytokine profile (TNFα and IL-12), suggesting a role of monocytes in antitumor immune responses against gliomas." (PMID 37304294, 2023). "For the downregulated genes in the combination treated tissue compared with the Ad-SGE-REIC-treated U87ΔEGFR glioma tissue, seven significantly enriched pathways were identified, including the Robo4 and VEGF Signaling Pathways Crosstalk and TNF-alpha NF-kB Signaling Pathway." (PMID 36006934, 2022). "Taking PTPN12 as an example, due to the significant correlation with cancer progression, we validated the potential function in glioma using GSEA and observed that PTPN12 contributed to several oncogenic pathways, including PI3K-AKT-mTOR signaling, and TNFα signaling." (PMID 36341348, 2022). "Although reduced TNFα production was observed in vivo, the combination therapy activated CD8+ T cell‐mediated immunity and increased survival in an immunoreactive mouse model carrying glioma." (PMID 35692083, 2022). "Acute ethanol exposure to astrocytes was found to enhance TNF-α- or interleukin-1β-induced upregulation of iNOS at 50 mM, as opposed to being suppressed at 200 mM in A172 human glioma cell line." (PMID 36431016, 2022). "To further investigate the significance of the TNFα inhibition on the GL261 syngeneic glioma mouse model tumorigenesis, we used MP6-XT22, the TNFα monoclonal antibody derived from rat, which is an analog of Infliximab, a chimeric monoclonal antibody directed at TNFα." (PMID 33853689, 2021). "In C6 glioma cells, the chaperone activity of HSPB1 contributed to the production of the pro-inflammatory cytokine, IL-6, whereas T cells from HSPB1−/− mice exhibited reduced secretion of TNF and IL-2." (PMID 33423680, 2021). "Furthermore, with a co-culture of G261 glioma cells and RAW 264.7 macrophages, we found that GL261 cell viability was related to chemotaxis of macrophages and TNF-α production." (PMID 34202555, 2021). "Furthermore, we show that inhibition of TNFα with antibodies or drugs, inhibits GAM-induced EC activation and improves survival in a mouse glioma model." (PMID 33853689, 2021). "Inhibition of TNFα blocks GAM-induced EC activation and improve survival in mouse glioma models." (PMID 33853689, 2021). "Minimal differences were noted in IFNγ, TNFα, Granzyme B, and CD107B expression when comparing CD4+ T cells from glioma patients before and after M032 treatment; however, a significant reduction in IL-4 production between pre- and post-M032 treatment in peripheral blood CD4+ T cells was noted." (PMID 35342877, 2021). "In 2004, a bivalent SM was highly effective in potentiating apoptosis when combined with TRAIL and TNFα but had no activity as a single agent in the T98G glioma cell line." (PMID 32325691, 2020). "The bivalent SMs were initially shown to potentiate the activity of TRAIL and TNFα but had no activity as a single agent in the T98G glioma cell line." (PMID 32325691, 2020). "Second, it is not easy to maintain glioma cells in a TNF-α/IL-6/sIL-6R contained micro-environment in the rat brain for differentiation therapy." (PMID 33227992, 2020). "Since CBD treatment of glioma cells strongly affected JNK pathway, notably MAPK p38 pathway and maintained relatively high basal NF-κB activity, we expected to find CBD-induced upregulation of TNFα gene expression." (PMID 29088769, 2017). "The use of AVs expressing tumor necrosis factor (TNF)-α or IFN-γ introduced into tumors enhanced infiltration of CD4 and CD8 positive T cells in addition to increasing expression of MHC class I and II on the tumor cells in a mouse glioma model." (PMID 26056588, 2014).
glioma (continued). "Therefore, the first goal of this study was to determine Cygb, PI3K, phosphorylated (p)-Akt, IL-6, TNFα and VEGF expression in gliomas." (PMID 23688241, 2013). "We immunohistochemically evaluated the expression of Cygb, phosphatidylinositol-3 kinase (PI-3K), phosphorylated (p)-Akt, Interleukin-6 (IL-6), tumor necrosis factor-α (TNFα) and vascular endothelial growth factor (VEGF) in 88 patients with 41 high-grade gliomas and 47 low-grade gliomas." (PMID 23688241, 2013). "TNF-α induces IL-6 release through the phosphorylation of NFκB, p38 mitogen-activated protein (MAP) kinase and stress-activated protein kinase (SAPK)/c-Jun N-terminal kinase (JNK) in rat C6 glioma cells." (PMID 20205746, 2010). "Elevated levels of A20 in GSCs contributed to apoptotic resistance: GSCs were less susceptible to TNFα-induced cell death than matched non-stem glioma cells, but A20 knockdown sensitized GSCs to TNFα-mediated apoptosis." (PMID 20186265, 2010). "TNFα increased apoptosis in non-stem glioma cells, consistent with prior results in glioma cell lines." (PMID 20186265, 2010). "In this report, we established that though p21cip/waf1 and p27kip1 are upregulated in response to TNF-α, p21 but not p27 is involved in the arrest of proliferation in TNF-α stimulated LN-18 glioma cells." (PMID 17565690, 2007). "Additionally, CD70 overexpression was detected in a multidrug-resistant colonic cell line (SW620-MDR), and as an inducible gene in TNF-alpha-stimulated human bronchial–epithelial cell line BEAS-2B, and irradiated glioma cell lines." (PMID 16892042, 2006). "In addition, we suppose that the extracellular matrix-related prognostic genes in MLDPS might influence the prognosis in AYAs glioma by activating the signaling pathways, such as NF-kB, PI3K-Akt, TNF and TGF-beta signaling pathway." (PMID 40774998, 2025). "In addition, ROR-α-induced TNF-α suppression resulted in downstream suppression of nuclear factor kappa B (NF-κB) signalling cascade, which plays a role in antiproliferative activities of ROR-α in glioma." (PMID 40495887, 2025). "In addition to susceptibility to cell death induced via the “intrinsic” apoptotic pathway, glioma and many other cancer cells can be induced to die by activation of the “extrinsic” pathway by ligands including TRAIL (tumor necrosis factor (TNF)-related apoptosis-inducing ligand)." (PMID 36831248, 2023). "The over-expression of PD-L1 and SIRPalpha along with lower expression of TIM-3 on the surface of non-classical monocytes and high expression of TNF and IL-12 suggests their dual role in promoting glioma-induced immunosuppression on the periphery and in stimulating the antitumor response." (PMID 36768201, 2023). "In addition, ELISA results indicated that CD8+ T‐cell supernatants cocultured with M2‐Exos‐cultured glioma cells had lower levels of IFN‐γ, TNF‐α, and Gzmb secretion; however, after adding the exosome inhibitor Annexin V or knocking down LINC01232, this phenomenon was reversed." (PMID 37097629, 2023). "In addition, ELISA results indicated that CD8+ T‐cell supernatants cocultured with LINC01232‐OE glioma cells showed lower levels of IFN‐γ, TNF‐α, and Gzmb secretion; however, knocking down NBR1 while overexpressing LINC01232 could also reverse this phenomenon." (PMID 37097629, 2023). "Furthermore, glioma-derived cytokines IL-1β, IL-6, and TNFα were observed to extend neutrophils lifespan from 7 h in normal conditions to 17 h in cancer, which in turn increases the number of neutrophils in peripheral blood." (PMID 38003396, 2023). "The remaining living glioma cells might be able to activate cGAS-STING1 pathway and release TNFα." (PMID 37292196, 2023). "Flow cytometry and real‐time quantitative PCR results indicated that CD8+ T cells cocultured with LINC01232‐OE glioma cells showed lower proliferation and expression of IFN‐γ, TNF‐α, and Gzmb; however, knocking down NBR1 while overexpressing LINC01232 could reverse this phenomenon." (PMID 37097629, 2023).
glioma (continued). "Therefore, to further confirm our hypothesis, we next examined the expression of several key inflammatories and immune modulators, including TNF-α, IL-2, IL-3, IL-4, and IL-12, in HK2-silenced T98 and GBM1 glioma cells." (PMID 35982398, 2022). "Also, TNFα has been shown to facilitate glioma invasion, not by upregulating MMP2 or MMP9, but through modulation of MEK-ERK1/2 pathway." (PMID 34975408, 2021). "Moreover, combination therapy of glioma with recombinant vaccinia virus mediated IL2 expression, resulted in significant tumor inhibition with concomitant elevation of NK, Mac-1+ and NKT cells in blood and IFNγ and TNFα expression in tumors." (PMID 33790740, 2021). "Therefore, we supposed that TNF‐α signalling induced the formation of a complex comprised of A20, TNIP1 and IKK, and this complex phosphorylated and induced IκB‐α degradation, leading to liberation of NF‐κB from the inhibitive condition in normal glioma cells." (PMID 31691497, 2020). "Following a 24 hours incubation of hEGFRvIII:CD3 bi-scFv, PBMCs, and human glioma cells U87-MG-EGFRvIII or control U87-MG cells, we harvested the supernatant and measured the concentration of IFN-ɣ, IL-6, IL-1β, MIP-1α, GM-CSF, and TNFα using the Luminex multiplex platform." (PMID 32273346, 2020). "Lastly, we have elaborated that TNF-α/IL-6/sIL-6R could downregulate the proliferation rate and the tumorigenicity of glioma cells, but not eliminate them." (PMID 33227992, 2020). "Thus, we analyzed the expression of a panel of common M1 (IL-1b, IL-12, iNOS, TNFα) and M2 (TGFβ, IL-10, ARG1) phenotype markers and the immune suppressive PD-L1 (CD274) in control and Pdpn-deleted BMDM co-cultivated with four different glioma cell lines." (PMID 30972297, 2019). "Moreover, gliomas induce GAMs to substantially decrease the expression of MHC molecules and pro-inflammatory cytokines (TNF-α) while increasing the secretion of transcription factor, STAT3, likely through S100B-receptor for advanced glycation end produces (RAGE) axis." (PMID 26217588, 2015). "The ability of tumor necrosis factor (TNF)-like weak inducer of apoptosis (TWEAK) to regulate NF-κB signaling and promote tumor progression was investigated in both established and primary high-grade glioma tumor lines using a three-dimensional (3-D) collagen invasion assay." (PMID 25622756, 2015). "Instead we demonstrate by immunoprecipitation experiments and mass spectrometry that the antigen recognized by the B-D13 antibody following cytokine stimulation is VCAM-1, and that VCAM-1, but not IL13Rα2, is induced on glioma cells by TNF alone or in combination with IL-13 or IL-4." (PMID 24787244, 2014). "Upregulation of TGFβ might be involved in promoting tumor proliferation and invasion, whereas TNFα is mainly produced by microglia because it has been found to be overexpressed in human glioma but not in isolated glioma cell lines." (PMID 22830012, 2012). "Other studies have reported an increase in cell content of S100B in C6 glioma cells after 24 h of exposure to IL-1β or no change in astrocyte cultures after 48 h and a decrease in S100B content in cultured astrocytes after 3 days of exposure to TNFα." (PMID 21970823, 2011). "However, Ser 276 is phosphorylated in unstimulated rat C6 glioma cells and the levels do not change with TNF-α stimulation." (PMID 20205746, 2010). "Interestingly, although TNF can induce EC apoptosis, it does not inhibit angiogenesis in glioma." (PMID 39033204, 2024).